RNU6-895P (RNA, U6 small nuclear 895, pseudogene)
Gene: Small nuclear RNA gene on chromosome 8 (41,298,163 to 41,298,265, forward strand). Ensembl gene ENSG00000206852.
Homologues: Orthologues: chimpanzee U6 (99% identical), macaque U6 (89% identical), dog U6 (75% identical), guinea pig U6 (70% identical). Paralogues in human: RNU6-1011P (82% identical), RNU6-12P (82% identical), RNU6-13P (82% identical), RNU6-145P (82% identical), RNU6-22P (82% identical), RNU6-32P (82% identical), RNU6-33P (82% identical), RNU6-49P (82% identical), RNU6-1 (81% identical), RNU6-1075P (81% identical), RNU6-1124P (81% identical), RNU6-17P (81% identical), and 1287 more.